YAP1 (Yes1 associated transcriptional regulator)
Diseases named in the same sentence as YAP1 in open-access papers (continued):
Sharing a sentence is not in itself a finding about the gene and the disease.
tumor (continued). "Moreover, YAP1 was performed, resulting in the same patient's normal tissues and tumor pairing (p = 0.0011)." (PMID 35449153, 2022). "Moreover, stromal fibroblasts of tumors coinjected with exosomes exhibited elevated levels of active YAP1 and FAPα, concomitant with an enhanced fibrotic response within tumor tissues." (PMID 35986369, 2022). "Moreover, it was reported that blockaded YAP1 can inhibit cell proliferation and relieve immune suppression within the tumor microenvironment in PDAC." (PMID 36008392, 2022). "In addition to known tumor-promoting genes, e.g., c-MYC, YAP1, RAD51B, TRIB3, SLC17A9, JADE1, we found that NAPRT, encoding a key enzyme for NAD+ biosynthesis from nicotinic acid, was also suppressed in HCC cells by the BRD4 inhibitor." (PMID 35399501, 2022). "In this study, nuclear YAP1 expression and tumor stiffness measured by SWE showed a significant correlation in linear and logistic regression analyses, which also means YAP1 expression could be a surrogate marker of tumor stiffness." (PMID 36291755, 2022). "In addition, Peptide 17 is able to repress N6-methyladenosine (m6A)’s methyltransferase 3 (METTL3) expression, leading to a decrease in YAP1 mRNA expression and of the consequent tumour-promoting effects in GC." (PMID 35565411, 2022). "Collectively our results suggested that EGFR, MAP2K1, mTOR, TEAD1, and YAP1 could mediate invasive tumor phenotypes and worsen prognoses via mechanisms involving both T-cell exclusion and dysfunctional phenotypes." (PMID 35655775, 2022). "MiR-6820-3p effected as a tumor suppressor to decrease YAP1 expression in PDAC." (PMID 36008392, 2022). "The Hippo signaling pathway is a highly conserved tumor suppressor pathway, mainly including Ste20-like kinase 1 (MST1) and large tumor suppressor 1 (LATS1), Yes associated protein 1 (YAP1) and its analog TAZ, and the regulatory subunits of MST1 and LATS1, MOB1 and SAV1." (PMID 35810157, 2022). "To investigate whether the function of SNHG16 in tumor progression is dependent on YAP1, we performed a rescue experiment." (PMID 36147462, 2022). "In addition, the overexpression of YAP1 rescued the inhibitory effect of SNHG16 knockdown on tumor metastasis." (PMID 36147462, 2022). "Our data suggest there may be an additional tumor-promoting function of YAP1 activation: the up-regulation of growth factors within the tumor microenvironment." (PMID 35930670, 2022). "Although we have demonstrated the important role of YAP1 in SNHG16 expression and tumor progression, the mechanism of the YAP1-lncRNA interaction remains largely unknown." (PMID 36147462, 2022). "Thus, YAP1 plays an important role in tumor progression by regulating the expression of target genes involved in proliferation, EMT, stemness and chemoresistance." (PMID 35407556, 2022). "We further showed that selective YAP inhibition in fibroblasts attenuated exosome-induced, YAP1-regulated fibroblast activation, suggesting that YAP1 inhibition might be a potential approach for attenuating tumor progression." (PMID 35986369, 2022). "While the in vivo tumor growth inhibition and biomarker modulation effects of the small molecule compound qualitatively compared to the effects we obtained with the YAP1 shRNA, the maximal tumor growth inhibition for K-975 was inferior to what we had observed with the genetic YAP1 shRNA knockdown." (PMID 35689194, 2022). "Collectively, the silencing of FBXW5 may reduce the entry of YAP1 into the nucleus and inhibit the growth of tumor xenografts." (PMID 35210431, 2022). "The immunohistochemical images showed HJURP/YAP1/NDRG1 axis promotes TNBC tumor growth." (PMID 35459269, 2022). "In these tumor cells, YAP1 forms a complex with TBX5 (T-box 5, a transcription factor)." (PMID 36532767, 2022). "Moreover, in the mouse tumor xenografts, linc01133 induced increased YAP1 expression both in the cytoplasm and in the nucleus, which were greatly ablated by simultaneous YES1 knockdown." (PMID 35017464, 2022).
tumor (continued). "Among them, the tumor-promoting role of YAP1 in COAD and PAAD has been determined experimentally." (PMID 36479120, 2022). "Whether YAP1-TEAD are drivers of tumor growth in some of these indications and whether YAP1 inhibition will suffice for in vivo activity on tumor maintenance remains to be established and will require similar genetic and pharmacological studies as shown here." (PMID 35689194, 2022). "Protein tyrosine phosphatase non-receptor type 14 (PTPN14) has been implicated as a tumor suppressor and negative regulator of YAP1." (PMID 35170430, 2022). "More importantly, YAP1 inhibitors attenuated AOM/DSS-induced inflammatory colonic adenocarcinoma in Villin-CXCR7 transgenic mice as well as impairing distant metastasis of HCT116LV-CXCR7 tumor xenografts in nude mice." (PMID 36210463, 2022). "YAP1 may promote tumor progression through immunosuppression, particularly by suppressing the infiltration of CD8+ T lymphocytes, CD4+ Th1 cells, T follicular helper cells, NKT cells, and activated NK cells, as well as recruiting MDSCs and CAFs in pan-cancer." (PMID 36479120, 2022). "Finally, wogonin inhibited the tumor growth in the mice and overexpression of YAP1 reversed the wogonin effects." (PMID 35037825, 2022). "YAP1 has also been shown to be regulated by metabolic pathways, such as aerobic glycolysis, mevalonate synthesis, and glutaminolysis during the development of tumor." (PMID 35810157, 2022). "Oncogene YAP1 plays an important role in maintaining tumor stemness." (PMID 35864972, 2022). "MT1-MMP, β1-integrin and YAP1 may be effective molecular markers for diagnosing and predicting tumor development." (PMID 35350840, 2022). "Tumor size measurements showed that YAP1 knockout significantly reduced tumor size." (PMID 35773411, 2022). "Moreover, we found H3K9me1/2 histone demethylase KDM3A as a novel downstream target of miR-335, and identified a new miR-335/KDM3A/YAP1 regulatory axis, which appears to play important roles in ccRCC tumor growth and metastasis." (PMID 33888871, 2022). "Therefore, RASAL2 increased TIAM1 expression and promoted the malignancy of tumor cells by upregulation of YAP1." (PMID 35844783, 2022). "Therefore, inhibiting the expression of YAP1 can effectively inhibit tumor migration and achieve the purpose of treatment." (PMID 35912206, 2022). "Congruently, the genes upregulated in tumor-draining LN fLECs, including several transcription factors that regulate lymphatic differentiation and lymphangiogenesis (Prox1, Klf4, Sox7, and Yap1), were significantly enriched for proliferation-, migration-, and angiogenesis-related GO terms." (PMID 35892863, 2022). "Hence, we evaluated the potential role of EGFR, MAP2K1, mTOR, and YAP1 in promoting the infiltration of tumor immune cells within the TME." (PMID 35655775, 2022). "Taken together, we speculated that quantitatively measured tumor stiffness by SWE might correlate with YAP1 activation that could be recognized by immunohistochemistry (IHC) of the nuclear expression of YAP1." (PMID 36291755, 2022). "In the past decade, increasing evidence has emerged to support the contribution of the dysfunctional Hippo pathway, especially core Hippo signaling effectors yes-associated protein 1 (YAP1) and WW domain-containing transcription regulator 1 (TAZ), in tumor initiation, progression, and recurrence." (PMID 36289774, 2022). "Collectively our results suggested that EGFR, MAP2K1, mTOR, TEAD1, and YAP1 could mediate invasive tumor phenotypes and produce worse prognoses via mechanisms involving both the T-cell exclusion and dysfunctional phenotypes." (PMID 35655775, 2022). "YAP1, as an oncoprotein, is inhibited by Hippo pathway in most tumor cells." (PMID 35281088, 2022).
tumor (continued). "Ursolic acid can downregulate the expression of YAP1 of the hippo pathway in tumor treatment." (PMID 35299895, 2022). "Finally, in vivo experiments showed that the inhibition of SNHG16 suppressed tumor progression, and that YAP1 rescued the effect of SNHG16 on tumor progression." (PMID 36147462, 2022). "These authors found that OTUB2 could directly act on YAP1/TAZ independently of the Hippo signaling pathway to promote tumor proliferation." (PMID 35850645, 2022). "Mechanistically, we confirmed that hsa_circ_0007367 could facilitate the expression of YAP1, a well-known oncogene, by sponging miR-6820-3p, which function as a tumor suppresser in PDAC cells." (PMID 36008392, 2022). "Furthermore, analysis of Reverse Phase Protein Assay (RPPA) data from TCGA revealed significantly higher YAP1 protein expression in C2 tumours." (PMID 36207323, 2022). "Further study suggested that overexpression of YAP1 could reduce the tumor suppressive effect of miR-375, and promote GC progression." (PMID 34345203, 2021). "Furthermore, to investigate the role of YAP1 in the regulation of tumor immunology in PAAD, we analyzed the relationships between YAP1 expression and marker genes of immune cells." (PMID 34150844, 2021). "Moreover, IHC staining results showed that HOXC10 knockdown caused a down-regulation of HOXC10, Slug, YAP1 and TAZ in the tumor tissues of mice." (PMID 35201457, 2021). "Thus, RASSF1A can use YAP1 to activate tumor suppressor genes, induce apoptosis and inhibit the oncogenic potential of YAP1." (PMID 34831091, 2021). "Negative hormone receptor status, tumor size >2 cm, and high nuclear YAP1 expression were significantly associated with decreased DMFS, as assessed by univariate analysis." (PMID 33718163, 2021). "Activated YAP1 contributes to cancer development by promoting a malignant tumor phenotype." (PMID 33718163, 2021). "In summary, HSPA7 facilitated tumor promoting macrophage migration into the GBM TME by activating the YAP1–LOX axis, and our results indicated that HSPA7 might be a potential immunotherapy target for GBM patients." (PMID 34354698, 2021). "Although the YAP1 S127A activating mutant is commonly used in cellular studies and tumor models, there is no corresponding active point mutation of YAP1 enriched in human cancer." (PMID 34150758, 2021). "Whether all these mechanisms for YAP1 activation and subsequent resistance to therapy exist in parallel and within the same tumor type or tumor cell requires further investigation." (PMID 34685695, 2021). "WWTR1 (also known as TAZ) and YAP1 as the major downstream effectors of the Hippo pathway are found not only to trigger numerous cell‐autonomous responses, but also to participate in choreographing tumour‐stromal interactions." (PMID 33660944, 2021). "Clustering analysis revealed nine RELA+, one YAP1+, and six unclassified tumours." (PMID 34314101, 2021). "The univariate analysis revealed YAP1 as a tumor suppressor in MM." (PMID 35059315, 2021). "Potential mechanisms may include activation of certain tumor suppressors while repressing some oncogenic pathways such as YAP1." (PMID 34717291, 2021). "On the other hand, YAP1 plays important role in maintaining redox balance in tumor cells." (PMID 34257617, 2021). "In addition, researchers found that YAP1 overexpression indirectly enhances drug resistance in tumor cells." (PMID 35071016, 2021). "YAP1 facilitates the growth of tumor cells and can lead to a poor prognosis in many cancers." (PMID 34953494, 2021). "However, in this study, the mRNA expression of YAP1 in tumor tissues was irrelevant to the clinicopathological characteristics or the survival of CMM patients." (PMID 33996543, 2021). "This evidence suggests that YAP1 is a potential therapeutic target, and that its pharmacologic or genetic inactivation may suppress tumor progression and improve drug sensitivity." (PMID 33718163, 2021). "This phenomenon showed that YAP1 level was negatively correlated with tumor burden in MM." (PMID 35059315, 2021).
tumor (continued). "Alternatively, MAGI proteins might indirectly control the YAP1 oncogenic pathway through the PTEN tumor suppressor." (PMID 34503076, 2021). "One tumour showing expression of YAP1+ signature genes was separated from the remaining tumours." (PMID 34314101, 2021). "Next, we evaluated the role of YAP1 in xenograft tumor growth in vivo." (PMID 33495462, 2021). "YAP1 might act either as an oncogene or tumour suppressor depending on its binding partner and its subcellular localization." (PMID 33611811, 2021). "Notably, it was reported that sequential targeting of YAP1 and p21 led to the elimination of senescent tumor cells." (PMID 34831091, 2021). "Given that YAP1 is hyperactive in many human cancers, it suggests that therapeutic targeting of YAP1 could regulate key processes in the tumor, thereby disrupting its survival mechanisms." (PMID 34446793, 2021). "Ribo-seq, RNA-seq, and RT-qPCR were applied to detect YAP1 expression in CMM mouse tumor tissues." (PMID 33996543, 2021). "YAP1 has been associated with processes such as proliferation and the recruitment of M2 macrophages, myeloid-derived suppressor cells (MDSC), and regulatory T cells to suppress host effector T cells in the tumor microenvironment." (PMID 34446793, 2021). "Dephosphorylated YAP1 acted as a co‐transcriptional factor through binding the transcriptional enhancer‐associated domain (TEAD) transcription factors to regulate downstream genes, which were involved in tumour initiation and progression." (PMID 33237585, 2021). "We proposed that YAP1-1 is more potent in promoting cancer cell malignancy in culture and primary tumor growth in vivo, whereas YAP1-2 has a more significant role in promoting metastasis due to its stabilization under low cell contact/density such as in the form of circulating tumor cells." (PMID 34094936, 2021). "Additionally, YAP1, a tumor suppressor, has been identified as an apoptotic factor induced by DNA damage in collaboration with p73 and promyelocytic leukemia." (PMID 34953494, 2021). "YAP1 functions as a transcriptional cofactor of the Hippo signaling pathway, a tumor suppressor pathway that controls organ size and tumorigenesis by sequestering YAP1 in the cytosol, whereas YAP1-MAMLD1 accumulates predominantly in the nucleus in ST-YAP1 tumors." (PMID 34885210, 2021). "Therefore, we used the TIMER database to explore the relationship between YAP1 expression and the degree of immune cell infiltration in 39 tumor types." (PMID 34150844, 2021). "The only YAP1 fusion‐positive tumour was detected in an infant girl." (PMID 34314101, 2021). "Most recently, YAP1 was reported to act as a contributor in inducing immunosuppressive tumor microenvironment by upregulating programmed cell death ligand 1 (PD-L1) or stimulating tumor cells to recruit tumor-infiltrating macrophages, MDSCs, and Tregs." (PMID 35059315, 2021). "Retrieval of DOX released a YAP1-dependent differentiation block and reduced tumor formation." (PMID 34294128, 2021). "Furthermore, YAP1 was highly expressed in tumor tissues in the TCGA datasets of COAD, and YAP1 was associated with advanced clinical characteristics of CRC." (PMID 34660259, 2021). "YAP1 expression was evaluated in both the cytoplasm and nuclei of the tumor cells." (PMID 33718163, 2021). "We did not detect significant associations between YAP1 levels and tumor purity or B cell, CD8+ T cell, neutrophil, and DC infiltration in STAD." (PMID 34150844, 2021). "The effect of MiR-21-3p on tumor phenotypes and YAP1 upregulation could be partly reversed via the restoration of SMAD7 expression in HCC cell lines." (PMID 33763375, 2021). "Our data also implicated that FAT1 might function as the tumor suppression through the promotion of the expression of PTPN14 and inhibition of the expressions of Yap1 and Myc." (PMID 34712552, 2021). "In addition, we performed WB analysis using the xenograft tumours, and found that the protein levels of YAP1 were up‐regulated in shPWAR6 group." (PMID 33834618, 2021).
tumor (continued). "Spearman test results indicated that YAP1 expression in Ribo-seq was negatively correlated with the weight of CMM mice after treatment (r = -0.735, p<0.05), while YAP1 expression in RNA-seq and RT-qPCR was irrelevant to tumor tissue weight (r=-0.347, p>0.05; r = -0.299, p>0.05)." (PMID 33996543, 2021). "In addition, the suppressive role of YAP1 in CHS tumor growth was further evaluated by subcutaneously inoculating the SC and shYAP1#4 stable cells into the nude mice at the right flank next to the forelimb." (PMID 33495462, 2021). "The YAP1 pathway is regulated by upstream Hippo tumour suppressors, including MST1/2 and LATS1/2." (PMID 34462427, 2021). "Moreover, miR-497 is able to function as a tumor-suppressor miRNA in NSCLC by targeting the vascular endothelial growth factor A (VEGF-A), cyclin E1 and the Yes-associated protein 1 (YAP1)." (PMID 33266470, 2020). "Consistently, it has previously been reported that VP may enhance the effects of gemcitabine and other anti-tumor drugs by inhibiting the expression of YAP1, by inhibition of autophagy or modulating lysosomal activity." (PMID 32218280, 2020). "However, the details of the YAP1 function in tumor cells is needed to be explored in future studies." (PMID 32190742, 2020). "Furthermore, YAP1-positive tumours in this early stage of development showed increased nestin expression and nestin was present in cells expressing nuclear YAP1 as well as those that had increased YAP1 in cytoplasm." (PMID 32404936, 2020). "HOPX co-localised with cells expressing nuclear YAP1 in LATS1/2 cKO tumours." (PMID 32404936, 2020). "Constitutive activation of YAP1/TAZ has been observed in many human tumours." (PMID 32633461, 2020). "Hippo proteins act as tumor suppressors that prevent the function of YAP1 and TAZ proto-oncogenes." (PMID 32722184, 2020). "Recent researches have pointed to an important role for YAP1 signaling in tumor progression." (PMID 32541093, 2020). "Overexpression YAP1 in tumor cell lines can induce EMT and enhances in vitro invasion." (PMID 32175692, 2020). "Suppression of YAP1 oncogenic activity with a subsequent modification of the tumor microenvironment may thus be an advantageous approach to control tumor growth and improve prognosis." (PMID 32054505, 2020). "VEGF-A interacting with NRP1 could regulate Hippo signaling to drive tumor cell survival, angiogenesis, and tumor formation through facilitating the stabilization of YAP1." (PMID 32046779, 2020). "Cytoplasmic and nuclear YAP1 staining was seen in 81% and 63% of tumours." (PMID 32488048, 2020). "Silencing YAP1 in tumour stromal cells can effectively inhibit tumour growth." (PMID 32066485, 2020). "Furthermore, the inhibition of miR-665 expression induced YAP1 to promote tumor proliferation, invasion, and metastasis." (PMID 33262782, 2020). "While YAP1-1 is more potent than YAP1-2 in promoting cancer cell malignancy in culture and primary tumor growth in vivo, YAP1-2 stabilized under low cell contact/density such as in CTCs, may contribute to cancer metastasis that merits future investigation." (PMID 32292505, 2020). "The expression of YAP1 in the tumour stroma may indicate the trend and prognosis of the disease, which provides new ideas and directions for cancer treatment in the future." (PMID 32066485, 2020). "This demonstrated that YAP1 indirectly affects the proliferation of epithelial cells through the regulation of stromal cells and that the highly expressed YAP1 stroma cells could effectively promote tumour growth." (PMID 32066485, 2020). "Overexpression of YAP1 partially rescued the tumour‐suppressing effects caused by IMUP silencing, suggesting that IMUP might promote tumorigenesis and progression of PTC via the HIPPO‐YAP1 pathway." (PMID 33094920, 2020). "Furthermore, we explored the relationship between YAP1 and tumor immune infiltration using CIBERSORT algorithm and GEPIA database." (PMID 33123286, 2020).